FOXO1 (forkhead box O1)
Description:
Transcription factor that is the main target of insulin signaling and regulates metabolic homeostasis in response to oxidative stress. Binds to the insulin response element (IRE) with consensus sequence 5'-TT[G/A]TTTTG-3' and the related Daf-16 family binding element (DBE) with consensus sequence 5'-TT[G/A]TTTAC-3'. Activity suppressed by insulin. Main regulator of redox balance and osteoblast numbers and controls bone mass (By similarity). Orchestrates the endocrine function of the skeleton in regulating glucose metabolism (By similarity). Also acts as a key regulator of chondrogenic commitment of skeletal progenitor cells in response to lipid availability: when lipids levels are low, translocates to the nucleus and promotes expression of SOX9, which induces chondrogenic commitment and suppresses fatty acid oxidation (By similarity). Acts synergistically with ATF4 to suppress osteocalcin/BGLAP activity, increasing glucose levels and triggering glucose intolerance and insulin insensitivity (By similarity). Also suppresses the transcriptional activity of RUNX2, an upstream activator of osteocalcin/BGLAP (By similarity). Acts as an inhibitor of glucose sensing in pancreatic beta cells by acting as a transcription repressor and suppressing expression of PDX1 (By similarity). In hepatocytes, promotes gluconeogenesis by acting together with PPARGC1A and CEBPA to activate the expression of genes such as IGFBP1, G6PC1 and PCK1 (By similarity). Also promotes gluconeogenesis by directly promoting expression of PPARGC1A and G6PC1. Important regulator of cell death acting downstream of CDK1, PKB/AKT1 and STK4/MST1. Promotes neural cell death. Mediates insulin action on adipose tissue (By similarity). Regulates the expression of adipogenic genes such as PPARG during preadipocyte differentiation and, adipocyte size and adipose tissue-specific gene expression in response to excessive calorie intake (By similarity). Regulates the transcriptional activity of GADD45A and repair of nitric oxide-damaged DNA in beta-cells (By similarity). Required for the autophagic cell death induction in response to starvation or oxidative stress in a transcription-independent manner. Mediates the function of MLIP in cardiomyocytes hypertrophy and cardiac remodeling (By similarity). Positive regulator of apoptosis in cardiac smooth muscle cells as a result of its transcriptional activation of pro-apoptotic genes. Regulates endothelial cell (EC) viability and apoptosis in a PPIA/CYPA-dependent manner via transcription of CCL2 and BCL2L11 which are involved in EC chemotaxis and apoptosis.
Synonyms: FKHR; FOXO1A; FKH1
Tractability: Small molecule: a structure with a bound ligand is known. PROTAC: UniProt records ubiquitination sites on it; ubiquitination databases record sites on it; its protein half-life has been measured; a small molecule that binds it is known.
Target class: Transcription factor
Gene: Protein-coding gene on chromosome 13 (40,555,667 to 40,667,612, reverse strand). Ensembl gene ENSG00000150907.
Subcellular location: Cytoplasm; Nucleus
Subcellular location (Human Protein Atlas): Nucleoplasm; Cytosol
Pathways (Reactome):
Gene expression (Transcription): FOXO-mediated transcription of cell cycle genes; FOXO-mediated transcription of cell death genes; FOXO-mediated transcription of oxidative stress, metabolic and neuronal genes; Regulation of FOXO transcriptional activity by acetylation; Regulation of localization of FOXO transcription factors
Developmental Biology: AKT-mediated inactivation of FOXO1A; Regulation of gene expression in beta cells
Signal Transduction: AKT phosphorylates targets in the nucleus; MAPK6/MAPK4 signaling
Disease: Constitutive Signaling by AKT1 E17K in Cancer
Immune System: Interleukin-4 and Interleukin-13 signaling
Gene Ontology:
Molecular function: beta-catenin binding; DNA-binding transcription activator activity, RNA polymerase II-specific; DNA-binding transcription factor activity; nucleic acid binding; protein binding; sequence-specific DNA binding; ubiquitin protein ligase binding; chromatin binding; DNA-binding transcription factor activity, RNA polymerase II-specific; protein phosphatase 2A binding; RNA polymerase II cis-regulatory region sequence-specific DNA binding; chromatin DNA binding; DNA binding; DNA-binding transcription repressor activity, RNA polymerase II-specific; promoter-specific chromatin binding
Biological process: apoptotic process; cellular response to hyperoxia; cellular response to starvation; negative regulation of apoptotic process; negative regulation of stress-activated MAPK cascade; positive regulation of apoptotic process; positive regulation of autophagy; positive regulation of DNA-templated transcription; positive regulation of gluconeogenesis; positive regulation of protein catabolic process; positive regulation of transcription by RNA polymerase II; cellular response to cold; cellular response to insulin stimulus; cellular response to nitric oxide; cellular response to oxidative stress; DNA damage response; energy homeostasis; fat cell differentiation; insulin receptor signaling pathway; intracellular glucose homeostasis; negative regulation of cardiac muscle hypertrophy in response to stress; negative regulation of DNA-templated transcription; negative regulation of fat cell differentiation; negative regulation of insulin secretion; positive regulation of smooth muscle cell apoptotic process; and 7 more
Cellular component: cytoplasm; cytosol; nucleoplasm; nucleus; chromatin; mitochondrion
Genetic constraint (gnomAD): Loss-of-function variants: 6 observed, 34.02 expected, observed/expected ratio (o/e) 0.18, 90% interval 0.096 to 0.35. The synonymous counts are far from expectation, so gnomAD's model fits this gene poorly and the ratio says little. Missense variants: 737 observed, 782.61 expected, observed/expected ratio (o/e) 0.94, 90% interval 0.89 to 1. Synonymous variants: 380 observed, 306.45 expected, observed/expected ratio (o/e) 1.24, 90% interval 1.14 to 1.35.
Homologues: Orthologues: chimpanzee FOXO1 (100% identical), macaque FOXO1 (99% identical), dog FOXO1 (95% identical), pig FOXO1 (95% identical), mouse Foxo1 (93% identical), rat Foxo1 (92% identical), tropical clawed frog foxo1 (68% identical), zebrafish foxo1a (58% identical), zebrafish foxo1b (52% identical). Paralogues in human: FOXO3 (44% identical), FOXO4 (32% identical), FOXO6 (29% identical), FOXM1 (14% identical), FOXK2 (12% identical), FOXC1 (12% identical), FOXJ2 (12% identical), FOXJ3 (12% identical), FOXL2 (12% identical), FOXN1 (12% identical), FOXD1 (11% identical), FOXC2 (11% identical), and 29 more.
Diseases named in the same sentence as FOXO1 in open-access papers:
FOXO1 is named in the same sentence as 498 diseases in open-access papers, as found by Europe PMC text mining. Sharing a sentence is not in itself a finding about the gene and the disease. The quoted sentences say what the papers report.
Insulin resistance (301 papers, 2005 to 2026). Increased resistance towards insulin, that is, diminished effectiveness of insulin in reducing blood glucose levels. "Atherosclerosis in low-density lipoprotein receptor KO mice caused insulin resistance in major arteries and decreased FoxO1 and FoxO3a phosphorylation, showing that FoxOs are activated in atherosclerotic vasculature." (PMID 40141412, 2025). "In cases of insulin resistance, phosphorylated Foxo1 translocates into the nucleus, where it associates with PGC-1α, thereby triggering the expression of target genes accounted for gluconeogenesis in the liver, such as G6p and Pepck." (PMID 41048434, 2025). "Post-transcriptional modifications of FOXO1, including phosphorylation, acetylation, and ubiquitination, are associated with insulin resistance and glucose homeostasis." (PMID 40287828, 2025). "Prototypical and pathological characteristics of type 2 diabetes mellitus (T2DM) such as peripheral insulin resistance and impaired β-cell compensation predisposes the β-cell to failure via impaired FOXO1 phosphorylation." (PMID 40585255, 2025). "Studies have shown that reduced AKT-dependent FOXO1 phosphorylation is associated with insulin resistance and apoptosis in DCM." (PMID 40313619, 2025). "In pancreatic β-cells, FOXO1 controls insulin release and β-cell survival, and FOXO1 upregulation is associated with β-cell dysfunction in obesity and the pathogenesis of insulin resistance and T2D." (PMID 40218884, 2025). "In the setting of systemic insulin resistance, the targeted removal of FoxO1 and FoxO3 specifically in cardiomyocytes was associated with the preservation of cardiac function." (PMID 38494853, 2024). "Molecular insights implicated that the sustained activation of FoxO1 contributed to the elevation of pIRS1 Ser levels, ultimately resulting in the development of insulin resistance." (PMID 38494853, 2024). "The FOXO1 gene has been associated with insulin resistance which is one of the key components of the equine metabolic syndrome (EMS)." (PMID 39118059, 2024). "Previous studies have shown that overexpression of FoxO1 in skeletal muscle is associated with insulin resistance and glucose intolerance." (PMID 39100099, 2024). "Mechanistically, co-exposure to DEHP and BPA causes liver dysfunction and hepatic insulin resistance via PI3K/AKT/FOXO1 pathway in offspring." (PMID 36976981, 2023). "As a result, mice with myeloid FoxO1 deficiency were protected from developing glucose intolerance, insulin resistance, and fasting hyperinsulinemia in response to prolonged HFD feeding." (PMID 35700043, 2022). "As suggested, the inert insulin resistance causes the activation of the FOXO-1 pathway promoting gluconeogenesis." (PMID 36479211, 2022). "In contrast, we showed that myeloid FoxO1 deficiency protected mice from developing diet-induced inflammation and insulin resistance, a beneficial effect that halted the progression of NAFL to NASH in MøFoxO1-KO mice on a NASH diet." (PMID 35700043, 2022). "The significance of endothelial FOXO1 activity in the promotion of atherosclerosis associated with insulin resistance has also been highlighted." (PMID 34381074, 2021). "Inhibition of FoxO1 affects age-associated insulin resistance and energy metabolism, particularly under normal dietary conditions." (PMID 34631216, 2021). "Residual glucose and insulin signaling-related proteins were detected and the mechanisms associated with the SIRT1/FOXO1 signaling pathway in insulin resistance explored." (PMID 32280711, 2020). "Insulin resistance of the skeletal muscle is associated with reduced activity of Akt kinase, and low Akt activity leads to the activation of FoxO1, which increases the MSTN mRNA levels in C2C12 myotubes." (PMID 32316589, 2020). "A previous study on mice demonstrated that FoxO1 deregulation is associated with insulin deficiency or insulin resistance." (PMID 30216660, 2018).
Insulin resistance (continued). "Our work revealed that FOXO1 O-GlcNAcylation is associated with heart insulin resistance and cardiac dysfunction." (PMID 30420836, 2018). "From the clinical point of view, upregulated FOXO-1 raises a state of insulin resistance and diabetes, due to a loss of insulin sensitivity, and the consequent hyperglycemia or high glucose accelerates cellular damage." (PMID 26839893, 2016). "The manual disease annotations for Foxo1 point to both T1D and T2D associations, as well as insulin resistance, heart failure, premature aging and, like TCF7L2, to pancreatic neoplasms." (PMID 27602200, 2016). "In diabetic conditions, insulin resistance causes Akt inactivation leading to greater FOXO1 activation due to reduced Akt activity; FOXO1, in turn, up-regulates genes that promote gluconeogenesis, such as Pgc1α and Atp5b, and increases serum glucose levels." (PMID 25226535, 2014). "We have previously performed a genomic analysis of FoxO1 targets in β-cells in order to investigate the mechanisms underlying β-cell adaptation to insulin resistance." (PMID 23705021, 2013). "Elevated Foxo1, which occurs under conditions of both insulin absence (type 1 diabetes) and insulin resistance (type 2 diabetes), is associated with increased triglyceride production in mice." (PMID 19424489, 2009). "Hepatic insulin resistance manifests predominantly as increased gluconeogenesis and fasting hyperglycemia, primarily associated with the dysregulation of forkhead box protein O1 (FoxO1) transcription factor." (PMID 41009549, 2025). "In adipose tissue, FOXO1 activates lipolysis by activating the expression of genes needed for fat degradation, while in obesity, its overactivation can cause an imbalance in the storage and mobilization of fat, which worsens insulin resistance." (PMID 40218884, 2025). "Furthermore, palmitate-induced insulin resistance in Hepa 1–6 was also associated with increase in glucose production and elevated expression of genes involved in gluconeogenesis- Foxo1, Pck1 and G6pc." (PMID 38745315, 2024). "However, a causal link between insulin resistance and increased FoxO1 expression following myocardin downregulation in Atp6v0d1AKO mice remains to be established." (PMID 38505620, 2024). "Thus, targeting FoxO1 is a promising strategy for the treatment of insulin resistance-associated metabolic diseases." (PMID 37960324, 2023). "Upregulation of miR-223 caused suppression of the FOXO1 protein, leading to insulin resistance." (PMID 36297381, 2022). "FKBP5 expression is associated with insulin resistance, and its activity is regulated by FOXO1." (PMID 35642195, 2022). "FoxO1,3,4 control carbohydrate and lipid metabolism during physiologic adaptations to fasting; their dysregulation directly impacts pathologic gene expression caused by insulin resistance, diabetes mellitus, and metabolic syndrome." (PMID 35362476, 2022). "The disruption of normal insulin signaling owing to hyperinsulinemia, insulin resistance, or absolute insulin deficiency associated with diabetes causes dysregulation of FoxO1 phosphorylation and subcellular localization, leading to improper FoxO1 activity and its target genes transcription." (PMID 33859563, 2021). "Furthermore, clinical evidence showing that genetic FOXO1 variants are associated with insulin resistance and type 2 diabetes also supports the contribution of FOXO1 in glucose metabolism in humans." (PMID 30249058, 2018). "FoxO1 and Glut4 are closely linked to insulin resistance and glucose intake, respectively." (PMID 28710412, 2017). "What could be the cause for persistent activation of FOXO1 in cardiac tissue in the settings of insulin resistance, lipid overload, elevated inflammatory cytokines and hyperglycemia?" (PMID 26956801, 2016).
Insulin resistance (continued). "Conversely, when IKK2 is superactivated in fasting liver or neonatal liver, where IKK1 is low and FOXO1 activity is high, FOXO1 synergizes with p65/p50 to cause insulin resistance and induce proinflammatory IL-1β, IL-6, CCL2, and CCL20, resulting in progressive inflammation and/or liver fibrosis." (PMID 26219821, 2015). "In cases where there is deficient inhibition of FOXO1 through insulin resistance, inflammation may be enhanced by greater cooperation between NF-κB and FOXO1." (PMID 24864265, 2014). "In summary, our results identify Ccn3 as a novel transcriptional target of FoxO1 that could underlie the adaptive response to insulin resistance." (PMID 23705021, 2013). "In view of the role of FoxO1 in β-cell compensation to insulin resistance, we reasoned that investigation of FoxO1 target genes could reveal mechanisms underlying β-cell failure in the context of insulin resistance." (PMID 23705021, 2013). "MSS may stimulate the PI3K/Akt/Foxo1 signaling pathway by mitigating chronic inflammation caused by a high-fat diet, therefore inhibiting excessive hepatic gluconeogenesis and ultimately improving insulin resistance." (PMID 42254421, 2026). "FOXO1 has been reported to mediate VD deficiency-induced insulin resistance in the skeletal muscle; however, the mechanistic links between VD signaling, gluconeogenesis, and insulin resistance in the liver remain unclear." (PMID 35132380, 2022). "MLB’s improvement of the HFD mice’s insulin resistance strongly suggested that the restoration of the PI3K-Akt pathway not only played a role in glucose metabolism but also had an inhibitory effect on the FoxO1/MAFbx and MuRF-1 pathways and reduced obesity-associated muscle atrophy." (PMID 35010979, 2021). "To test this hypothesis, we set out to undertake a new context to determine the gene expression of PPAR-γ2, C/EBP-α and FOXO1 from morbidly obese individuals with high and low insulin resistance in VAT, to understand their association with obesity and insulin resistance." (PMID 31547433, 2019). "This AKT-mediated phosphorylation of FOXO1 at T24 is known to inactivate FOXO1, thereby improving hyperglycemia and insulin resistance in diabetes patients." (PMID 40287828, 2025). "It other studies, it was demonstrated that pancreatic cancer-derived exosomes induce insulin resistance in recipient cells through the PI3/Akt/FOXO1 signaling pathway, highlighting their role in altering cellular function." (PMID 40699634, 2025). "Inhibition of FOXO1 activity by AS1842856 in insulin resistance conditions (palmitate + glucose) increased elastin and decreased MMP-9 expression compared to palmitate and glucose alone." (PMID 41049496, 2025). "Curcumin ameliorated hepatic steatosis and insulin resistance by downregulating the hepatic c-Jun N-terminal kinase 2 (JNK2)/Fork head box protein O1(FOXO1)/B-cell lymphoma 6 (Bcl6) axis and altering the composition and structure of the intestinal flora." (PMID 41368575, 2025). "In insulin resistance, Akt activation is inhibited, resulting in increased FOXO1 entry and enhanced gluconeogenesis." (PMID 39761309, 2025). "FOXO1 promotes hepatic glucose production and regulation of lipid metabolism, which, in the presence of insulin resistance, leads to hyperglycemia and dyslipidemia." (PMID 40951426, 2025). "In mice with obesity and insulin resistance, Foxo1 ASO-therapy resulted in lower plasma glucose levels and reduced endogenous glucose production." (PMID 39944202, 2025). "The study underscores the role of oleate in modulating beta cell function, suggesting that its influence on FoxO1 activity contributes to the failure of beta cell adaptation in the context of obesity-induced insulin resistance." (PMID 39940428, 2025).